CYP2J2 (cytochrome P450 family 2 subfamily J member 2)
Diseases named in the same sentence as CYP2J2 in open-access papers (continued):
Sharing a sentence is not in itself a finding about the gene and the disease.
Arrhythmia (3 papers, 2013 to 2023). Any cardiac rhythm other than the normal sinus rhythm. "We found that targeting CYP2J2 affected the expression of multiple sodium, potassium and calcium ion channels, several of which have been associated with the pathogenesis of cardiac dysrhythmias." (PMID 32210298, 2020). "Combined with the results of the present study, we can now conclude that the epoxy-metabolites produced by CYP2J2 or stabilized upon sEH inhibition exert a direct antiarrhythmic effect that protects the heart from arrhythmia even under conditions of severe hypertrophy and pump failure." (PMID 24023684, 2013). "The same PES protocols that were effective in WT mice did not induce cardiac arrhythmias in any of the CYP2J2-TG animals 4 weeks after sham or TAC operation." (PMID 24023684, 2013).
hepatocellular carcinoma (3 papers, 2017 to 2022). A malignant tumor that arises from hepatocytes. "For example, 6,8-diprenylorobol indicated an anticancer effect that induced apoptosis in hepatocellular carcinoma cell lines by inhibiting cytochrome P450 family 2 subfamily J member 2 (CYP2J2) and activating forkhead box O3 (FOXO3)." (PMID 35052675, 2022).
ischemic stroke (3 papers, 2017 to 2023). A stroke disorder caused by obstruction of blood flow to the brain, due to thrombotic (local blood clot formation) or embolic (due to a blood clot or other material traveling from another site) event. "Studies have shown that CYP2J2 gene polymorphisms can affect the occurrence and development of ischemic stroke by modulating transcriptional activity." (PMID 34666595, 2021). "High Hcy level can downregulate CYP2J2 protein expression and upregulate sEH protein expression in vitro and in vivo, thus attenuating the protective effect against ischemic stroke by reducing the production of EETs." (PMID 28409162, 2017).
preeclampsia (3 papers, 2013 to 2019). Preeclampsia is a hypertensive disorder of pregnancy that is characterized by new-onset hypertension with proteinuria presenting after 20 weeks of gestation, and depending on mild or severe forms may initially present with severe headache, visual disturbances, and hyperreflexia. "TNF-alpha induces collagen I deposition in the maternal vasculature, and MMP1 and -7 activity induce extracellular matrix degradation, while CYP2J2, elevated in preeclampsia, may also be involved in uteroplacental and vascular remodeling." (PMID 31252672, 2019). "However, consistent with these findings, CYP2J2 is up-regulated in preeclampsia and is induced in a trophoblast cell line with TNFα." (PMID 24058654, 2013).
atrial fibrillation (2 papers, 2013 to 2020). A disorder characterized by an electrocardiographic finding of a supraventricular arrhythmia characterized by the replacement of consistent P waves by rapid oscillations or fibrillatory waves that vary in size, shape and timing and are accompanied by an irregular ventricular response. "The aim of the present study was to determine whether CYP2J2/EET has a preventive effect on atrial fibrillation (AF) and to investigate the underlying mechanisms." (PMID 31749335, 2020). "In contrast to WT mice, CYP2J2-TG mice were largely protected against the development of atrial fibrillation inducibility." (PMID 24023684, 2013). "Two weeks after ISO treatment, CYP2J2-TG mice showed an atrial fibrillation inducibility of about 17% (4 out of 24 protocols in 8 animals) that was significantly lower than in the corresponding WT group." (PMID 24023684, 2013). "CYP2J2-overexpression reduced the vulnerability towards ventricular tachyarrhythmia after chronic pressure overload (TAC model), and suppressed atrial fibrillation inducibility after chronic β-adrenergic stimulation (ISO model)." (PMID 24023684, 2013). "CYP2J2-overexpression protected against AERP shortening and atrial fibrillation induction." (PMID 24023684, 2013).
cardiomyopathy (2 papers, 2019 to 2020). A disease of the heart muscle or myocardium proper. "Given the multifaceted function of CYP2J2, we initially determined CYP2J2 protein levels in cardiac tissue obtained from patients with cardiomyopathy and control subjects." (PMID 32210298, 2020). "Using a proteomic approach, we found that CYP2J2 expression is lower in cardiac tissue from patients with cardiomyopathy compared to controls." (PMID 32210298, 2020). "In two distinct studies, endothelial and cardiovascular tissue-specific overexpression of CYP2J2 in diabetic mice reduced nephropathy and cardiomyopathy, which are important diabetic comorbidities." (PMID 31269743, 2019). "In this study, we first investigated CYP2J2 protein levels using proteomic mass spectrometry in ventricular tissue obtained from a cohort of individuals without heart disease (controls) and patients with cardiomyopathy." (PMID 32210298, 2020).
Cognitive impairment (2 papers, 2016 to 2022). Abnormal cognition is characterized by deficits in thinking, reasoning, or remembering. "CYP2J2 variants are involved in promoting cerebrovascular disease and their polymorphisms are associated with susceptibility to cognitive impairment." (PMID 37008043, 2022). "Furthermore, patient DCP300407 with only HOOK1, CYP2J2 and C1orf87 deleted displays cognitive impairment." (PMID 26997977, 2016).
colorectal cancer (2 papers, 2023). A primary or metastatic malignant neoplasm that affects the colon or rectum. "We also investigated p-p38, CYP2J2 and sEH in human grade 2 colorectal carcinoma tissues and adjacent normal tissues." (PMID 37175404, 2023). "In contrast to p38 and sEH, CYP2J2 immunostaining intensities were comparable in normal adjacent tissue and colorectal carcinoma (p = 0.3984)." (PMID 37175404, 2023).
diabetic kidney disease (2 papers, 2021 to 2023). Progressive kidney disorder caused by vascular damage to the glomerular capillaries, in patients with diabetes mellitus. "Previous studies have shown that single nucleotide polymorphisms (SNPs) in CYP2J2, CYP2C8, CYP2C9, and EPHX2 are associated with diabetes and diabetic kidney disease (DKD); however, their genetic effects on GDM remain unclear." (PMID 37370090, 2023).
glioblastoma (2 papers, 2020 to 2022). The most malignant astrocytic tumor (WHO grade IV). "Expression of CYP2J2 in U87 cells, a human glioblastoma cell line, significantly decreased when miRNA-584 was co-transfected in the cells." (PMID 32486275, 2020). "MiR-584 suppresses various cancer include glioblastoma, by attaching to 3-UTR on Cytochrome P450 Family 2 Subfamily J Member 2 (CYP2J2) reduced proliferation and invasion of glioblastoma cells." (PMID 36536420, 2022).
glioma (2 papers, 2020 to 2022). A benign or malignant brain and spinal cord tumor that arises from glial cells (astrocytes, oligodendrocytes, ependymal cells). "CYP2J2 knockdown using shRNA enhanced the anti-glioma effect of JWH133 by abrogating the increased expression of 11,12-EET." (PMID 33330047, 2020). "Combination treatment of JWH133 and CYP2J2 shRNA significantly enhanced the anti-glioma effect of JWH133." (PMID 33330047, 2020). "M2 polarisation also proved to be the mechanism by which the CB2 agonist JHW-133 attenuated its own tumour-regressive effect in nude mice with intracranial glioma xenografts, which was only fully expressed by knockdown of cytochrome P450 2J2 (CYP2J2), which mediates the proangiogenic effect." (PMID 35277658, 2022). "This study showed that targeting CYP2J2 might be a beneficial strategy to enhance the anti-glioma efficacy of JWH133 by inhibiting the pro-angiogenesis function of M2 microglia." (PMID 33330047, 2020). "Herein, we hypothesized that JWH133 treatment can exert anti-glioma action, concurrently leading to microglial M2 polarization in glioma, which promotes glioma growth via enhancing angiogenesis by increasing the expression of CYP2J2 and 11,12-EET, an isomer of EETs." (PMID 33330047, 2020). "CYP2J2 knockdown restrained the release of 11,12-EET and significantly enhanced the anti-tumor effect of JWH133 on glioma." (PMID 33330047, 2020). "These lines of evidence showed the involvement of the ERK/CYP2J2/11,12-EET singling pathway in the pro-glioma effect of M2 microglia/TAMs after JWH133 treatment, thus presenting a promising therapeutic target." (PMID 33330047, 2020). "Additionally, administration of the CB2 antagonist—AM630—abolished the anti-glioma effect of JWH133 and abrogated the activation of ERK pathway and the increased expression of CYP2J2/11,12-EET after JWH133 treatment." (PMID 33330047, 2020). "Next, our results showed that CYP2J2 disruption by lentivirus-shRNA inhibited tumor growth in vivo (*P < 0.05 vs. U87 + Control shRNA), but did not impact the growth of glioma cells in vitro (not significant vs. Control shRNA)." (PMID 33330047, 2020). "However, JWH133 also promoted microglia/TAMs M2 polarization in the glioma, which weakened its anti-glioma effect; therefore, the JWH133-induced M2 phenotypic cells facilitated angiogenesis by releasing 11,12-EET via activating the ERK/CYP2J2 pathway." (PMID 33330047, 2020).
ischemic cardiomyopathy (2 papers, 2020 to 2022). Ischemic cardiomyopathy is a cardiomyopathy in which a weakness in the muscle of the heart due to inadequate oxygen delivery to the myocardium with coronary artery disease being the most common cause. "In a recent study assessing CYP2J2 expression in cardiac tissue from patients with unspecified non-ischemic cardiomyopathy there was a marked reduction in this enzyme." (PMID 35665247, 2022). "We utilized mass spectrometry to assess whether CYP2J2 protein content differed between individuals without cardiac disease and patients with non-ischemic cardiomyopathy." (PMID 32210298, 2020).
leukemia (2 papers, 2011 to 2019). A malignant (clonal) hematologic disorder, involving hematopoietic stem cells and characterized by the presence of primitive or atypical myeloid or lymphoid cells in the bone marrow and the blood. "In another study, CYP2J2 is reported to be highly expressed in human and mouse hematological cell lines, as well as in peripheral blood and bone marrow cells of leukemia patients." (PMID 31139078, 2019). "It has been recently reported that CYP2J2 was absent in human leukocytes, but present at high levels in malignant hematological (lymphocytic) cell lines and in leukemia cells from peripheral blood and bone marrow in patients with malignant hematologic diseases." (PMID 22028915, 2011).
liver cancer (2 papers, 2021 to 2022). An epithelial or non-epithelial malignant neoplasm that arises from the liver. "In addition, 6,8-diprenylorobol suppressed cell viability and induced apoptosis in human liver cancer cells (HCC) via regulation of FOXO3 and CYP2J2." (PMID 35052675, 2022).
liver failure (2 papers, 2023 to 2024). A liver disease characterized by the liver losing or has lost all of its function. "However, recent data indicate that the two cytochrome isoenzymes CYP2J2 and CYP4F2 metabolize linezolid which may be influenced by liver failure and thus could explain the reduced body clearance in ACLF as shown in our study." (PMID 37698659, 2023).
metabolic syndrome (2 papers, 2018 to 2019). A cluster of metabolic risk factors for CARDIOVASCULAR DISEASES and TYPE 2 DIABETES MELLITUS. "The CYP2J locus containing CYP2J2 in humans and its synteny with mice and rats shows a reduced allelic expansion in the rat, suggesting that the rat is a more appropriate model to study the role of P450 epoxygenases in adipogenesis and metabolic syndrome." (PMID 29656108, 2018).
pulmonary arterial hypertension (2 papers, 2018 to 2021). Pulmonary arterial hypertension (PAH) is a group of diseases characterized by mean pulmonary artery pressure >20 mmHg and elevated pulmonary arterial resistance leading to right heart failure. "In monocrotaline-induced pulmonary hypertensive Sprague–Dawley rats, CYP2J2 gene therapy also attenuated development and vascular remodeling associated with pulmonary hypertension." (PMID 29966295, 2018). "However, the role of CYP2J2 and EETs in pulmonary arterial hypertension (PAH) with lung ischemia–reperfusion injury (LIRI) remains unclear." (PMID 34774051, 2021).
Sepsis (2 papers, 2017 to 2024). Sepsis is defined as life-threatening organ dysfunction caused by a dysregulated host response to infection. "We found that relative to uninfected controls, human neonates with clinical sepsis exhibited significantly reduced expression of ALOX15, PTGS2 and CYP2J2, implicating all main AA metabolic pathways in sepsis." (PMID 38769383, 2024). "In order to evaluate the protective effect of CYP2J2 against LPS induced sepsis, endothelial specific 2J2 transgenic mice were used." (PMID 28881620, 2017).
abdominal aortic aneurysm (1 paper, 2018). Enlargement and ballooning of the vessel that supplies arterial blood to the abdomen, pelvis and legs. "Overexpression of aortic CYP2J2 via a recombinant adeno-associated virus in angiotensin-II induced abdominal aortic aneurysm apolipoprotein E-deficient mice led to higher EET levels, which activated PPAR and inhibited inflammatory responses." (PMID 29966295, 2018).
acute kidney injury (1 paper, 2022). Sudden and sustained deterioration of the kidney function characterized by decreased glomerular filtration rate, increased serum creatinine or oliguria. "EETs derived from CYP2J2 overexpression protected I/R-induced rat acute kidney injury (AKI) through activation of autophagy by upregulating the Sirt1/FOXO3a signaling pathway." (PMID 35744996, 2022).
acute monocytic leukemia (1 paper, 2011). Acute monoblastic leukemia (AML-M5), is one of the most common subtypes of acute myeloid leukemia (AML) that is either comprised of more than 80% of monoblasts (AML-M5a) or 30-80% monoblasts with (pro)monocytic differentiation (AML-M5b). "Although we found CYP2J2 and CYP2C8 mRNA in human total leukocytes, lymphocyte and monocyte fractions (but not PMNs), the levels of mRNA were consistently lower than those found in our THP-1 cells (a human acute monocytic leukemia cell line)." (PMID 22028915, 2011).
asthma (1 paper, 2023). "Additionally, CYP2J2 is related to asthma models and cancer." (PMID 36825998, 2023).
attention deficit-hyperactivity disorder (1 paper, 2024). A disorder characterized by a marked pattern of inattention and/or hyperactivity-impulsivity that is inconsistent with developmental level and clearly interferes with functioning in at least two settings (e.g. at home and at school). "CYP2J2 was associated with attention deficit hyperactivity disorder (ADHD), aging, educational attainment, and levels of vitamin D, dopamine metabolites, and phenol sulfate." (PMID 39457450, 2024).
bronchitis (1 paper, 2023). An acute or chronic inflammatory process affecting the bronchi. "Four SNPs in CYP2J2 were found to be associated with the Chinese Han population with COPD-S, and even in the Russian population, SNPs in CYP2J2 are associated with bronchitis secondary to smoking." (PMID 36825998, 2023).
cardiac ischemia (1 paper, 2017). "While CYP2J2 overexpression has shown beneficial effects on vasodilation, inflammation, and contractile recovery from cardiac ischemia, the relevance of CYP2J2 metabolism in CRH had not been previously explored." (PMID 28328948, 2017).
cataract (1 paper, 2019). Partial or complete opacity of the crystalline lens of one or both eyes that decreases visual acuity and eventually results in blindness. "In CC54, 5 genes (ANAPC1, RPIA, IGF2BP2, CYP2J2 and LRIG1) and 1 disease (Cataract) were extracted as a correlated set." (PMID 31345171, 2019).
Cerebral ischemia (1 paper, 2017). Restriction of arterial blood supply to the brain associated with insufficient oxygenation to support the metabolic requirements of the tissue. "In male mice, endothelial overexpression of human CYP2J2 (Tie2-CYP2J2 Tr) enhanced blood flow and suppressed inflammation to protect against experimental cerebral ischemia." (PMID 28328948, 2017).
chronic lung disease (1 paper, 2022). According to the definitions of the American and British Thoracic Societies, including pulmonary functional tests, X-rays, and CT scans for items such as fibrosis, bronchiectasis, bullae, emphysema, nodular or lymphomatous abnormalities. "Our results generally illustrate the potential therapeutic role of the CYP2J2-EET-sEH pathway in chronic lung disease." (PMID 36275905, 2022). "Regulating CYP2J2-EET-sEH metabolic pathway may be a potential therapeutic option for PF and chronic lung diseases." (PMID 36275905, 2022).
colorectal adenocarcinoma (1 paper, 2020). The most common type of colorectal carcinoma. "Although mRNA transcripts of CYP epoxygenases (CYP2Cs and CYP2J2) in colorectal adenocarcinoma patients in TGCA database did not change compared with controls, transcripts of CYP epoxygenases and protein expression of CYP2C9 were significantly increased in primary human colorectal adenocarcinoma." (PMID 32581794, 2020).
Crohn disease (1 paper, 2013). A gastrointestinal disorder characterized by chronic inflammation involving all layers of the intestinal wall, noncaseating granulomas affecting the intestinal wall and regional lymph nodes, and transmural fibrosis. "Using epoxygenase/CYP2J2 inhibitors reveals a dysregulation in bacterial clearance which is also a hallmark of Crohn’s disease." (PMID 24058654, 2013). "Here we investigated the role of CYP2J2 in bacterial phagocytosis and its expression in monocytes from healthy controls and Crohns disease patients." (PMID 24058654, 2013). "The rested macrophages from Crohn’s disease patients similar to healthy controls had low levels of CYP2J2." (PMID 24058654, 2013). "We therefore examined CYP2J2 in Crohn’s disease macrophages." (PMID 24058654, 2013). "Here we show CYP2J2 is induced by bacterial stimulation, but is absent in Crohn’s disease macrophages." (PMID 24058654, 2013). "In contrast macrophages derived from Crohn’s disease patients showed no induction of CYP2J2 with heat-treated E. coli." (PMID 24058654, 2013). "Unlike macrophages from control donors, macrophages from Crohn’s disease patients showed no induction of CYP2J2 in response to E. coli." (PMID 24058654, 2013). "Since CYP2J2 appears particularly dysregulated, our results suggest EET mimetics and/or sEH inhibitors may be of particular benefit in Crohn’s disease." (PMID 24058654, 2013). "CYP2J2 was one of the un-validated targets absent specifically in Crohn’s disease (but not ulcerative colitis) macrophages treated with heat inactivated E. coli." (PMID 24058654, 2013). "The lack of CYP2J2 in response to inflammation may therefore mediate some of the macrophage defects observed in Crohn’s disease." (PMID 24058654, 2013). "An absence of CYP2J2 in Crohn’s disease macrophages in response to bacterial infection may contribute to the pathogenesis of Crohn’s disease, in part via a reduced expression of CD11b." (PMID 24058654, 2013).
endothelial dysfunction (1 paper, 2025). In vascular diseases, endothelial dysfunction is a systemic pathological state of the endothelium (the inner lining of blood vessels) and can be broadly defined as an imbalance between vasodilating and vasoconstricting substances produced by (or acting on) the endothelium. "Moreover, reduced EET bioavailability has been linked to endothelial dysfunction, oxidative stress, and adverse cardiac remodeling in HF (CYP2J2 Modulates Diverse Transcriptional Programs in Adult Human Cardiomyocytes)." (PMID 41472876, 2025). "Dysregulation among these nodes—characterized by reduced PLA2G2A and GGT5 expression together with elevated CYP2J2 and EPHX2—may reflect a disrupted AA-EET axis that favors oxidative stress, endothelial dysfunction, and maladaptive cardiac remodeling, ultimately contributing to HF progression." (PMID 41472876, 2025).